MT1H (metallothionein 1H)
Description:
Metallothioneins have a high content of cysteine residues that bind various heavy metals; these proteins are transcriptionally regulated by both heavy metals and glucocorticoids.
Synonyms: MT-1H; MT-0; MT-IH; MT1
Tractability: PROTAC: ubiquitination databases record sites on it.
Gene: Protein-coding gene on chromosome 16 (56,669,814 to 56,671,129, forward strand). Ensembl gene ENSG00000205358.
Pathways (Reactome):
Cellular responses to stimuli: Metallothioneins bind metals
Gene Ontology:
Molecular function: protein binding; metal ion binding; zinc ion binding
Biological process: cellular response to cadmium ion; cellular response to zinc ion; cellular response to copper ion; detoxification of copper ion; intracellular zinc ion homeostasis; negative regulation of growth
Cellular component: cytoplasm; nucleus
Genetic constraint (gnomAD): Loss-of-function variants: 9 observed, 10.73 expected, observed/expected ratio (o/e) 0.84, 90% interval 0.5 to 1.46. The upper end of that interval is the gene's LOEUF score, 1.46, which puts it in group 6 of 6, group 1 being the genes least tolerant of losing a copy. Missense variants: 84 observed, 77.97 expected, observed/expected ratio (o/e) 1.08, 90% interval 0.9 to 1.29. Synonymous variants: 32 observed, 30.46 expected, observed/expected ratio (o/e) 1.05, 90% interval 0.79 to 1.41.
Homologues: Orthologues: zebrafish mt2 (62% identical). Paralogues in human: MT1HL1 (95% identical), MT1G (90% identical), MT2A (90% identical), MT1A (89% identical), MT1X (89% identical), MT1B (87% identical), MT1F (87% identical), MT1M (80% identical), MT3 (72% identical), MT4 (64% identical), MT1E (52% identical).
Diseases named in the same sentence as MT1H in open-access papers:
MT1H is named in the same sentence as 27 diseases in open-access papers, as found by Europe PMC text mining. Sharing a sentence is not in itself a finding about the gene and the disease. The quoted sentences say what the papers report.
prostate carcinoma (9 papers, 2016 to 2023). A carcinoma that arises from epithelial cells of the prostate gland. "The co-expressed genes, MT1E and MT1H, were previously associated with tumour invasion in bladder, glioma, liver and prostate cancer respectively." (PMID 32636408, 2020). "Induced MT1H expression can inhibit cell growth by reducing colony formation and the entry of prostate cells into S and M phases in prostate cancer." (PMID 38068944, 2023). "As observed in HCC and prostate cancer, the formation of the MT1h-GLP complex is critical for the MT1h tumor-suppressive effect, as a mutation in MT1h inhibits GLP binding and abolishes the tumor-suppressive activity of MT1h." (PMID 35740522, 2022). "MT1h is a tumor suppressor protein that belongs to a class of metal binding proteins that is downregulated in human malignancies such as liver and prostate cancers." (PMID 35740522, 2022). "Intriguingly, decreased expression of MT1H impaired the colony formation and interfered with prostate cancer and HCC cells entering the S and M cell cycle phases to suppress cell growth." (PMID 34676244, 2021). "Notably, one group of genes with very strong negative correlations (≤-0.9) to radiomic features were found to be associated with the AR signaling genes: KLK2, KLK3, HOMER2, BMPR1B, or belong to validated prostate cancer classifiers: CHRNA2, MT1H, DPP4, MYBPC1." (PMID 27438142, 2016). "Methylation inactivation in tumor suppressors genes, such as MT1M, MT1H, MT1X, and HRK, is responsible for the development of various cancers, such as prostate cancer, liver cancer, colorectal cancer, and gastric cancer, but loss of these genes may be linked with the pathogenesis of BRCA." (PMID 31311202, 2019).
hepatocellular carcinoma (8 papers, 2017 to 2025). A malignant tumor that arises from hepatocytes. "Previous studies have linked the down-regulation of MT1F, MT1G, and MT1H to hepatocellular carcinoma, and the down-regulation HOXA to breast cancer with the whole cluster silenced." (PMID 32841292, 2020). "MT1H functions as a suppressor in hepatocellular carcinoma by regulating the Wnt/beta-catenin pathway." (PMID 40495885, 2025). "MT1H plays tumor-suppressing roles by regulating the Wnt/β-catenin signaling pathway in hepatocellular carcinoma, and interacts with EHMT1, which promotes its methyltransferase activity in prostate malignancies." (PMID 38833013, 2024). "They found that MT1H could suppress Wnt/β-catenin signaling to inhibit tumor progression, including hepatocellular cancer cell proliferation, invasion, and migration." (PMID 30139373, 2018). "A similar suppressive role of MT1H was also reported in hepatocellular carcinoma." (PMID 30139373, 2018). "Likewise, the matrigel-uncoated transwell assay showed that ectopic overexpression of MT1H significantly impaired the migration capability of hepatoma cells as compared with the vector control cells (right)." (PMID 28241806, 2017).
colorectal cancer (2 papers, 2019). A primary or metastatic malignant neoplasm that affects the colon or rectum. "Collectively, these results indicate that high expression of MT1B, MT1H, or MT1L correlates with good prognosis in colorectal cancer patients." (PMID 31394742, 2019).
gastric cancer (2 papers, 2019). A primary or metastatic malignant neoplasm involving the stomach. "Notably, DNA methylation of some MT isoforms in gastric cancer, like MT1A, MT1B, MT1H, MT1M, MT3, and MT4, was higher than their paired normal tissue except remaining isoforms." (PMID 31380415, 2019).
lung carcinoma (2 papers, 2021 to 2024). "For lung cancer, MT1H overexpression results in enhanced cisplatin resistance." (PMID 38833013, 2024). "Hence, the upregulation of MT1B, MT1F, MT1G, and MT1H in HPAEpiCs after exposure to PHMG may be involved in the development of lung cancer." (PMID 34564354, 2021).
psychosis (2 papers, 2008 to 2023). "Using a quantitative PCR, we validated a set of genes such as up-regulated metallothioneins (MT1E, MT1F, MT1H, MT1K, MT1X, MT2A and MT3) and down-regulated neuropeptides (SST, TAC1 and NPY) in the dorsolateral prefrontal cortex of psychosis patients." (PMID 18992145, 2008). "In the current cross-study analysis, we identified a set of metallothionein genes including MT1X, MT1K, MT1E, MT1H, MT1F, MT2A and MT3 that are significantly up-regulated in psychosis." (PMID 18992145, 2008). "In a study conducted on postmortem subjects with and without psychosis, up-regulation in MT1E, MT1F, MT1H, MT1K, MT1X, MT2A, and MT3 genes was observed in the dorsolateral prefrontal cortex." (PMID 36831126, 2023).
melanoma (1 paper, 2021). A malignant, usually aggressive tumor composed of atypical, neoplastic melanocytes. "According to the analysis of human melanoma scRNA-seq, myeloid cells associated with responders showed a relatively high expression of PLTP, APOC1, APOE, MT1G, and MT1H." (PMID 34966676, 2021).
nutritional deficiency (1 paper, 2022). "Paneth cell markers were also downregulated in EED chips compared with healthy chips in control medium (for example, MT2A, CFTR and MT1H were suppressed by ~2–2.5-fold, respectively), but were differentially regulated when chips were exposed to nutritional deficiency." (PMID 35739419, 2022).
pancreatic cancer (1 paper, 2023). "The co-expressed genes of the NT5DC family, including UGT2B7, MT1G, ACADL, MT1H, and others, were found to be associated with pancreatic cancer in previous studies 37-40." (PMID 37576396, 2023).
Parkinson disease (1 paper, 2023). A progressive degenerative disorder of the central nervous system characterized by loss of dopamine producing neurons in the substantia nigra and the presence of Lewy bodies in the substantia nigra and locus coeruleus. "Metallothioneins are up-regulated in neurodegenerative disorders and in metabolic stress; both MT1H and MT1F were up-regulated in substantia nigra and frontal cortex of Parkinson’s disease patients." (PMID 37629120, 2023).
viral infection (1 paper, 2020). "In relevance to viral infection, MT1F, MT1G, and MT1H proteins exerted some amount of antiviral activity against Hepatitis C viruses (HCV), while HOXA10 was shown to suppress Hepatitis B viruses (HBV) replication." (PMID 32841292, 2020).
tumor (21 papers, 2015 to 2024). "Acting as a hypermethylated gene and implicating an epigenetic property of alcohol-associated HCC, MT1H has already exhibited its latent capacity of turning into epigenetic markers for this subtype of neoplasia." (PMID 34676244, 2021). "MT1h exerts its role as a tumor suppressor by activating euchromatin histone methyltransferase 1 (EHMT1), which leads to histone methylation and potentially suppresses gene expression." (PMID 38169461, 2024). "MT1H functions as a tumor suppressor that suppresses the proliferation and invasion of HCC cells by inhibiting the Wnt/β-catenin pathway." (PMID 35300417, 2022). "The tumor tissues derived from basal, Her2, LumA, and LumB breast tissues were not significantly different between normal and tumor ones; for MT1H the expression levels are displayed in the box plot." (PMID 34572798, 2021). "It is important to explore the tumor suppressor role of MT1H mediated by Wnt/β-catenin signaling in HCC." (PMID 28241806, 2017). "We investigated the expression level of MT1H in the Cancer Genome Atlas (TCGA) dataset and a panel of 12 paired tumor/non-tumor tissues." (PMID 28241806, 2017). "Downregulation of MT1H was observed in TCGA dataset and a panel of 12 paired tumor/non-tumor tissues." (PMID 28241806, 2017). "Moreover, tumor cells showed lower expression of the metallothionein family genes, including MT1H and MT1G." (PMID 35974387, 2022). "The MT1H has low expression and serves as a tumor suppressor in prostate cancer." (PMID 34572798, 2021). "MT1H may function in regulating cellular response to zinc ions and negatively modulate tumor growth via the downregulation of the inflammatory pathway, Jak–STAT pathway, TNF pathway, and Wnt signaling pathway." (PMID 34676244, 2021). "Similarly, HOXA10, LEFTY1, and MT1H have all been suggested to act as tumor suppressors, whose overexpression leads to a better prognosis." (PMID 32841292, 2020). "Therefore, it is rational to deduce that tumor suppressive role of MT1H on HCC is attributed, at least partly, to the inhibition of Wnt/β-catenin signaling." (PMID 28241806, 2017). "Thus, we hypothesize that MT1H may make a crucial contribution to tumor growth by governing the supply of zinc during a period when cells get ready to undergo DNA synthesis." (PMID 34676244, 2021). "Similarly, low expression and tumor suppressor activity of MT1H were identified in prostate cancer." (PMID 30139373, 2018). "Consistently, the results in current study from TCGA database and paired fresh tumor/non-tumor tissues showed significantly decreased MT1H expression in HCC tissues." (PMID 28241806, 2017). "As for MT1H and MT1G, it is known that metallothioneins (MTs) represent a class of proteins involved in processes of cellular detoxification from ROS and heavy metals and, through this mechanism, they might act as tumor-suppressor genes." (PMID 25945129, 2015).
cancer (8 papers, 2015 to 2022). A tumor composed of atypical neoplastic, often pleomorphic cells that invade other tissues. "The promoter region of MT1H was hypermethylated in cancer, and conversely, demethylation of the MT1H promoter reversed the suppression of MT1H expression." (PMID 34676244, 2021). "The findings from the present study are also helpful for a better understanding of the link between trace elements and HCC by suggesting the possible role of serum Cu concentrations and of MT1G/MT1H promoter methylation in cancer tissues as prognostic factors in HCC." (PMID 33585212, 2020). "Strikingly, members of the metallothionein family, including MT1M, MT1H, MT1G, MT1F, MT1E, MT1X, and MT1A, were significantly downregulated in cancer cells." (PMID 35967424, 2022). "While down-regulated genes were associated with GO categories such as cellular response to zinc ion where members of metallothionein family (MT1M, MT1H, MT1X, MT1G, and MT1F) play important roles in carcinogenesis of various cancer types." (PMID 32849813, 2020). "Additionally, we found that nearly half of these 21 edges involved a protein of the Metallothionein family (i.e. MT1H, MT2A, MT1HL1, MT1X and MT1G), involved in the regulation of transcription factors and in cancers." (PMID 34197603, 2021).
MT1H also shares sentences with these, for which no sentence is quoted: breast carcinoma (2 papers); glioma (2); periodontal disease (2); retinoblastoma (2); Alzheimer disease (1); amyloidosis (1); colon cancer (1); colorectal tumor (1); Down syndrome (1); Hepatic fibrosis (1); infection (1); liver cancer (1); neurological disorders (1); transitional cell carcinoma (1).